EPO (erythropoietin)
Diseases named in the same sentence as EPO in open-access papers (continued):
Sharing a sentence is not in itself a finding about the gene and the disease.
anemia (continued). "Beyond the clinical use of EPO for treating anemia, EPO can influence glucose and fat metabolism in adipose tissues, skeletal muscle and the liver." (PMID 41012526, 2025). "Our research indicates that the erythropoietin resistance index (ERI) is not only a biomarker for the treatment response of anemia in maintenance hemodialysis (MHD) patients but also a predictor of stroke and all-cause mortality risk." (PMID 41244199, 2025). "Epoetin Alfa is a recombinant erythropoietin (EPO) traditionally used for anemia treatment; however, it has been discovered that both EPO and its receptor (EPO-R) are widely expressed in the central and peripheral nervous systems." (PMID 40343008, 2025). "This creates a pathological feedback loop where kidney dysfunction exacerbates iron dysregulation, contributing to erythropoietin resistance and anemia progression." (PMID 41266138, 2025). "For decades, recombinant EPO has been prescribed as an effective therapy for cancer-related anemia and fatigue, significantly improving patients’ quality of life while reducing their dependence on blood transfusions." (PMID 41375075, 2025). "Our study demonstrated that intravenous iron therapy was significantly effective than oral iron in improving hemoglobin levels and other anemia-related parameters in diabetic patients with CKD receiving erythropoietin." (PMID 40980376, 2025). "In adults, EPO, produced by interstitial cells in the kidney, is inducible under hypoxic conditions and increases in response to anemia, high altitude, or ischemic stress." (PMID 39996752, 2025). "These deleterious effects limit the patient populations that can benefit from EPO‐based ESAs, and therefore, an ESA that only activates the EPOR homodimer would be highly desirable as an alternative to pleiotropic EPO for the treatment of anemia." (PMID 40960423, 2025). "It is worth to mention that exogenous recombinant erythropoietin is a well-established therapeutic agent for the treatment of anemia, particularly in patients with end-stage renal disease." (PMID 39881295, 2025). "The pathophysiology of anaemia in CKD involves both a reduced erythropoietin production due to impaired renal function and the effects of inflammation, which impair iron metabolism and erythropoiesis." (PMID 41153672, 2025). "The pathogenesis of this anemia is multifactorial, with mechanisms including impaired production of erythropoietin, dysregulated iron homeostasis, and the suppressive effects of inflammation and uremic toxins on erythropoiesis." (PMID 40773297, 2025). "Roxadustat not only can improve anemia and iron metabolism, but also can reduce serum cholesterol and triglyceride levels in PD patients after switching from the EPO." (PMID 40000368, 2025). "Tumor-associated inflammation elevates hepcidin levels, sequesters iron, shortens red cell lifespan, and diminishes erythropoietin responsiveness, resulting in anemia of inflammation." (PMID 41210883, 2025). "These inhibitors have been widely used in the clinical management of anemia associated with chronic kidney disease (CKD) due to their ability to mimic hypoxic conditions and promote endogenous EPO synthesis." (PMID 40141384, 2025). "The current patient experienced anemia resistant to erythropoietin and iron supplements with several previous blood transfusions accompanied by elevated ferritin." (PMID 39758152, 2025). "Table shows no marked association between vitamin B6 level and other parameters of anemia, duration of dialysis, erythropoietin dose, or the frequency of blood transfusion." (PMID 39871236, 2025). "Another important regulatory axis involves erythroferrone (ERFE), a hormone secreted by erythroblasts in response to erythropoietin stimulation, particularly during anemia and hypoxia." (PMID 40872496, 2025). "In contrast, erythropoietin supplementation bypasses these risks and directly supports erythropoiesis, offering a safer and more targeted approach for managing anemia in LPI patients." (PMID 39881295, 2025).
anemia (continued). "Physiologically, anemia is expected to stimulate counterregulatory increase in erythropoiesis reflected by increased renal EPO secretion and reticulocyte count." (PMID 40225399, 2025). "Kidney diseases represent a state of dysfunction of this source of circulating EPO, which results in the anemia of chronic kidney disease (CKD) that is multi‐factorial in pathophysiology, with endocrine EPO deficiency playing a major role." (PMID 40960423, 2025). "In bone marrow, excessive ROS impairs hematopoietic stem cell renewal, promoting senescence and apoptosis, which contribute to erythropoietin-resistant anemia." (PMID 41516280, 2025). "PTH, for example, promotes anemia by reducing endogenous erythropoietin production and shortening red blood cell survival." (PMID 41157262, 2025). "In anemia treatment, EPO release significantly increased hematocrit levels, reaching 76.3 ± 2.3 % within three weeks from a baseline of over 20 %." (PMID 40547419, 2025). "Diabetes-related chronic hyperglycemia tends to induce a hypoxic environment in the renal interstitium, which results in the impaired production of erythropoietin by the peritubular fibroblasts and subsequent anemia." (PMID 41383345, 2025). "Repeated injection of recombinant human EPO and its derivatives has been shown to be effective in preventing anemia and has been used as a treatment for decades." (PMID 40221815, 2025). "EPO is commonly administered to hemodialysis patients to increase hemoglobin levels, given the dialysis-induced anemia." (PMID 40370459, 2025). "Although EPO is clinically approved for treating anemia in both neonates and adults, further evaluation is needed to establish its safety and tolerability when repurposed for metabolic indications across these populations." (PMID 40697664, 2025). "Two anemic rat models were establishedto determine the ERFE and erythroid responses to rHuEPO under conditionsof impaired EPO responsiveness (i.e., CKD-associated anemia) and reducedprecursor cells (i.e., CIA)." (PMID 39816799, 2025). "ASCO’s guideline adaptation similarly advises that there is insufficient evidence to routinely prescribe medications for CRF, apart from treating underlying conditions (like antidepressants for depression, or erythropoietin for chemotherapy-induced anaemia)." (PMID 40498265, 2025). "Cobalt chloride and roxadustat are hypoxia mimetics that increase erythropoietin production and can treat anemia by inhibiting PH3, although they can also suppress other PHs (depending on the dose)." (PMID 41155680, 2025). "In conclusion, roxadustat not only can improve anemia and iron metabolism, but also can reduce serum cholesterol and triglyceride levels in PD patients after switching from the EPO therapy." (PMID 40000368, 2025). "In neonatal intensive care, red blood transfusions or erythropoietin are commonly used to maintain appropriate hemoglobin and hematocrit levels in preterm infants to prevent anemia." (PMID 41108422, 2025). "In contrast, hypoxia and anemia stimulate erythropoietin (EPO) production, which contributes to the synthesis and secretion of erythroferrone by nucleated erythrocytes, effectively downregulating hepcidin expression." (PMID 40092979, 2025). "Pure red cell aplasia is characterized by the development of NAbs against erythropoietin, leading to severe anemia, low reticulocyte count, erythroblast absence, and epoetin nonresponse." (PMID 41441633, 2025). "In parallel, the oxidative environment described in Section 3 adversely affects hematopoiesis, reducing hematopoietic stem cell self-renewal and impairing erythroid differentiation, which promotes the erythropoietin-resistant anemia observed in advanced CKD." (PMID 41516280, 2025). "The anemia is multifactorial, attributed to a decrease in erythropoietin production, a slowdown in bone marrow maturation, or even concomitant malabsorption (particularly of iron or folates)." (PMID 40709115, 2025).
anemia (continued). "Zhou and Vaziri examined the changes in plasma EPO concentration and urinary EPO excretion in response to hypobaric hypoxia and experimentally induced anemia via phlebotomy and volume replacement in nephrotic and control rats." (PMID 40620843, 2025). "Renal failure-related platelet defect: Correction of anemia conventionally by erythropoietin and less commonly by transfusion was shown to decrease uremic bleeding." (PMID 41306494, 2025). "Clinicians should consider implementing HRR-guided strategies to optimize anemia management, including targeted erythropoietin therapy, iron supplementation, and transfusion protocols, while also addressing underlying inflammatory processes." (PMID 41386280, 2025). "Subcutaneous implantations are also commonly chosen for diabetes treatment (42 %), but also notably when showing proof of concept of a new device (24 %), and treatment of anemia via EPO secretion (13 %)." (PMID 40547419, 2025). "When kidney function impairs due to various reasons including diabetic mellitus or hypertension, erythropoietin cannot be made, leading to anemia." (PMID 39807510, 2025). "A reduction in erythropoietin levels, commonly seen in individuals with chronic kidney disease, can also lead to the development of anemia." (PMID 39931366, 2025). "Clinical studies show that parathyroidectomy in ESRD patients with secondary hyperparathyroidism improves anemia, erythropoietin production, and responsiveness." (PMID 41157262, 2025). "Chronic kidney disease (CKD) often leads to anemia due to both lower EPO levels and limited iron availability." (PMID 41007630, 2025). "Two of the most used ESAs for treating anemia in CKD patients are recombinant human erythropoietin and darbepoetin alfa." (PMID 40027896, 2025). "Anemia related to PH, which is resistant to erythropoietin, has been described and is mostly accompanied by debilitating bone pain, generalized skeletal osteosclerosis, osteopenia, and deformities." (PMID 39758152, 2025). "The Kidney Disease Improving Global Outcomes (KDIGO) guidelines recommend initiating iron therapy only for anemia-related indications, i.e., increasing hemoglobin (Hb) levels and minimizing the use of EPO-stimulating agents." (PMID 41034675, 2025). "Anemia of CKD: Anemia of CKD occurs because failing kidneys produce less erythropoietin (EPO), leading to normocytic anemia." (PMID 40001516, 2025). "Reduced erythropoietin (EPO) production leads to anemia, exacerbating fatigue, hypoxia, and cardiac strain, further worsening HF outcomes." (PMID 40278183, 2025). "The result indicates that Roxadustat can still stabilize Hb concentrations when the doses were gradually tapered in PD patients with anemia who previously were treated with EPO." (PMID 40000368, 2025). "While anemia is involved in renal dysfunction progression, reduced EPO production due to renal dysfunction leads to anemia." (PMID 41385514, 2025). "For patients with low red blood cell counts, nurses should regularly evaluate anemia status and implement measures such as iron, vitamin B12, or erythropoietin supplementation to ameliorate anemia." (PMID 40687754, 2025). "In both experimental models, anemia progressed from day 10 to day 30, in spite of increased circulating erythropoietin levels." (PMID 40643488, 2025). "Correction of preoperative anemia using intravenous iron or erythropoietin, based on local protocols, is mandatory." (PMID 41157288, 2025). "Anemia is a common, multifactorial complication due to CKD but is mainly attributable to insufficient erythropoietin production, iron deficiency, and chronic inflammation." (PMID 41040470, 2025). "Numerous clinical trials demonstrated the efficacy of r-EPO in managing cancer-related anemia and in preventing and correcting anemia resulting from cytotoxic treatments." (PMID 41375075, 2025).
anemia (continued). "M1 was also enriched in heme biosynthesis and erythrocyte-related genes: alterations in erythrocyte counts are well-known in HDP, and EPO treatment is commonly used to address anemia in these individuals." (PMID 40370459, 2025). "The main reason for anemia in patients with IMN is that the kidneys gradually lose the ability to produce EPO during disease progression." (PMID 40568201, 2025). "The introduction of recombinant human erythropoietin (rhEPO) in 1989 improved anemia management but also raised concerns about adverse cardiovascular outcomes in many studies." (PMID 41179057, 2025). "They underscore the central role of splenomegaly in VL‐related anaemia and suggest potential contributions from other factors affecting iron metabolism, such as erythropoietin and erythroferrone." (PMID 40637365, 2025). "Maintaining adequate iron levels is crucial to prevent anemia, increased EPO-stimulating agent dose requirements, and blood transfusions." (PMID 41034675, 2025). "Treatment with SGLT2is has been shown to ameliorate anemia through various mechanisms, including increased erythropoietin production and erythropoiesis, as well as the improved regulation of iron homeostasis." (PMID 40573204, 2025). "Recombinant human erythropoietin (rhEPO) is an active glycoprotein secreted by the kidneys that improves anemia." (PMID 41268443, 2025). "Renal insufficiency, a common comorbidity in HIV, can lead to reduced erythropoietin production and subsequent anaemia, further complicating the clinical management." (PMID 39901231, 2025). "Despite its central role in oxygen homeostasis and erythropoiesis, the molecular underpinnings of renal EPO production remain incompletely characterized, limiting therapeutic advancements for anemia." (PMID 41012526, 2025). "The pathogenesis of anemia in CKD is multifactorial, involving reduced erythropoietin production, iron deficiency, chronic inflammation, and the dysregulation of iron metabolism, which is closely linked to disturbances in phosphate and mineral homeostasis." (PMID 41155502, 2025). "Reduced erythropoietin (EPO) production, insufficient to counteract anemia, and a diminished response of erythroid progenitors to EPO are crucial underlying mechanisms." (PMID 41013345, 2025). "When comparing patients with CKD with or without anemia, reticulocyte production index was significantly lower whereas plasma EPO concentrations were slightly increased in those with anemia." (PMID 40225399, 2025). "EPO remains central to anemia correction, and its administration has been shown to improve graft survival and reduce all-cause mortality in transplant recipients." (PMID 41458512, 2025). "When anemia or low oxygen levels occur, renal cells sense the reduced oxygen supply and respond by increasing EPO production through HIF-2 signaling." (PMID 41007630, 2025). "Factors that are associated with the development of malarial anaemia include haemolysis, dyserythropoiesis, erythrophagocytosis and bone marrow suppression, with studies reporting varying erythropoietin (epo) responses to severe anaemia." (PMID 41050847, 2025). "We used specific keywords such as chronic kidney disease (CKD), iron-deficiency anemia (IDA), hemoglobin, erythropoietin (EPO), and iron." (PMID 39958087, 2025). "In cases such as ischemic stress or anemia, EPO synthesis decreases, leading to an advanced decline in red blood cell production." (PMID 41020856, 2025). "Although anemia can be a consequence of CKD because of decreased erythropoietin production, this finding would be unexpected in IRIS stage 1–2 cats, which constitutes the majority of the SUB cats in our study." (PMID 40947676, 2025). "Other contributing factors to anemia in diabetic patients include chronic inflammation, elevated levels of advanced glycation end products (AGEs), erythropoietin resistance, oxidative stress, and the side effects of anti-diabetic medications." (PMID 40655101, 2025).
anemia (continued). "PRCA induced by EPO should take into account when there is progressive anemia during EPO use, the combination of Roxadustat with immunotherapy being a more beneficial therapeutic alternative." (PMID 41012526, 2025). "EPO has been successfully used for anemia with slow erythropoietic compensation in neonates and infants from other etiologies such as anemia of prematurity in attempt to try to avoid transfusions." (PMID 41007072, 2025). "Anemia, frequently observed in CKD, is primarily attributable to erythropoietin deficiency and disordered iron metabolism." (PMID 41303873, 2025). "The glycoprotein hormone erythropoietin (EPO) is produced by the peritubular interstitial cells of the kidney in response to cellular hypoxia or anaemia." (PMID 39946495, 2025). "Although the relationship between erythropoietin and melatonin is still under study, regular erythropoietin administration leads to the correction of anemia and partial restoration of the nocturnal rise in melatonin in murine models." (PMID 39940247, 2025). "The possibility that the hematocrit drives changes in glycemia was further supported by mice treated with phenylhydrazine (PHZ), which induces hemolysis and anemia while triggering a counterregulatory rise in circulating EPO." (PMID 40238885, 2025). "The weak negative correlation (r = −.036) in CKD stage 5 indicated that uremia, erythropoietin usage and anemia all impair HbA1c reliability." (PMID 41190245, 2025). "The use of recombinant human erythropoietin has shown promise in some studies as an adjunct therapy for managing anemia in these patients." (PMID 41146772, 2025). "Simultaneously, tumor necrosis factor-alpha suppresses erythroid progenitor differentiation in the bone marrow and diminishes erythropoietin responsiveness, further exacerbating anemia." (PMID 40687061, 2025). "The high rate of parenteral prescriptions (69.33%) was largely due to erythropoietin, which is essential in anemia management." (PMID 41583201, 2025). "Background/Objectives: Chronic kidney disease (CKD) is commonly complicated by anemia resulting from impaired erythropoietin (EPO) production, iron dysregulation, and chronic inflammation." (PMID 41227183, 2025). "In response to anemia, the host tries to compensate by increasing the production of erythropoietin (EPO), a hormone which promotes erythropoiesis and stimulates the generation of reticulocytes, the immature red blood cells." (PMID 40871363, 2025). "The first, a UK Health Technology Assessment (HTA), evaluated erythropoietin for chemotherapy‐induced anaemia in cancer patients." (PMID 40873470, 2025). "Randomized controlled trials assessing erythropoietin-stimulating agents (ESAs) or placebo in adults with chronic kidney disease (CKD)-related anemia were included." (PMID 41249974, 2025). "Specifically, anaemia in PHD3‐KO animals resulted in twice the EPO mRNA abundance as in anaemic controls (28‐fold vs. 13‐fold increase)." (PMID 40853869, 2025). "Such a decrease in the level of EPO can lead to the worsening of anemia in patients undergoing chemotherapy." (PMID 40076818, 2025). "Recombinant human erythropoietin (rHuEPO) and darbepoetin alfa (DA) are key treatments for anemia in individuals with chronic kidney disease (CKD), including children, but evidence comparing their efficacy in the pediatric population remains inconclusive." (PMID 40349276, 2025). "In CRS-4, anaemia is predominantly due to depressed erythropoietin (EPO) production secondary to CKD and damage to peritubular fibroblasts." (PMID 40944787, 2025). "This type of anemia may be associated with several age-related physiological mechanisms, such as declining renal function, androgen deficiency, chronic low-grade inflammation associated with aging (inflammaging), myelodysplastic syndromes and impaired response to EPO." (PMID 40126293, 2025).